TNF (tumor necrosis factor)
Diseases named in the same sentence as TNF in open-access papers (continued):
Sharing a sentence is not in itself a finding about the gene and the disease.
Cachexia (continued). "Further examination of mitochondrial DNA deletion in skeletal muscle when the mouse cachexia model was treated with neutralizing antibodies against HMGB1 and TNFα showed mitochondrial DNA deletion in the non-antibody-treated group but not in the antibody-treated group." (PMID 39000167, 2024). "Indeed, several studies of HF, including HF-induced cachexia, have shown a negative correlation between the irisin concentration and hs-CRP, TNF-alpha, and interleukin-6." (PMID 39200291, 2024). "From this profile, when compared to that of the control group, it appears that serum levels of all cytokines were significantly higher in the cachexia group, and six cytokines (IL-1β, IL-2, IL-8, IL-12, TNF-α, and IFN-γ) were significantly higher in the group with advanced Pca without cachexia." (PMID 28050120, 2016). "Moreover, increased level of inflammatory markers was noted in cachectic patients compared to women without symptoms of cachexia (median CRP level: 10.95 mg/L (1.96–26.20) and 3.10 mg/L (1.45–4.95); p = 0.005; median TNF-α level: 4.48 pg/mL (3.49–5.13) and 3.29 pg/mL (3.07–4.91); p = 0.032)." (PMID 32260434, 2020).
Autoimmunity (365 papers, 2005 to 2026). The occurrence of an immune reaction against the organism's own cells or tissues. "IL-6 was linked with worsening disability in MS patients, while TNF-α was linked to a family history of autoimmunity." (PMID 41771986, 2026). "Given safety and economic concerns associated with mAb-based therapies for treatment of autoimmune conditions, this study investigated the potential of peptide-based TNF-α inhibitors as alternative therapeutic agents." (PMID 40338229, 2025). "In contrast, there was enrichment of mutations associated with autoimmunity and lymphoproliferation via TNF-α/NF-κB and the RAS pathways in cases with IEI variants associated with immunodeficiency." (PMID 40309770, 2025). "This trend was also visualized with IP-10, a chemokine downstream of interferon gamma (IFN-γ), and TNF-α, a cytokine implicated in chronic inflammation and autoimmunity and also associated with PCCs." (PMID 38312212, 2024). "TNF-α is a pro-inflammatory cytokine implicated in the pathogenesis of several autoimmune conditions." (PMID 39411715, 2024). "ANAs, which are linked to several primary autoimmune conditions and CTDs, are frequently generated due to anti-TNF-α therapy." (PMID 37833861, 2023). "While tumor necrosis factor (TNF) is a critical mediator of appropriate immune response and tissue repair, its misregulation is linked to cancer, autoimmunity, bone marrow failure, and aging." (PMID 36968066, 2023). "Beyond MHCII molecules, additional factors associated with the MHC locus are known to play a role in autoimmunity, such as numerous complement factors and several important cytokines including TNF-α." (PMID 38090594, 2023). "More recently, TNFα has been reported to induce the inflammasome-independent production of IL-1β, causing autoimmunity." (PMID 35269395, 2022). "RIP3, as an effector protein of the bifurcation point of TNF-α promoting apoptosis and necrosis, plays a key role in the regulation of necroptosis caused by viral bacterial infections, autoimmunity and other reasons." (PMID 35346043, 2022). "It has recently been reported that TNFα induces the inflammasome-independent production of IL-1β, causing autoimmunity." (PMID 33562074, 2021). "In summary, the presence of IF-ANA and probably disease-specific ANA before anti-TNF therapy were closely related to ADrA appearance, suggesting an association of immunogenicity with autoimmunity." (PMID 33315881, 2020). "- LPS activates microglial TLRs, training these cells excessively and triggering the release of C1q, TNF-alpha, and IL-1 alpha, biomolecules associated with autoimmunity." (PMID 30564191, 2018). "Pathway analyses revealed significant enrichment of antibody targets associated with immunity/autoimmunity, including TNFα signaling, toll-like receptor signaling and microRNA biogenesis." (PMID 29606147, 2018). "Pro-inflammatory cytokines, such as TNF-α and IL-6, have been shown to pose a multitude of biological effects linked to autoimmunity, and acute or chronic inflammatory diseases." (PMID 30486383, 2018). "In the context of autoimmunity, Treg suppressive function is optimized by pathogenic T cells and TNFα is one of factors involved in this optimization." (PMID 29619032, 2018). "These newly formed TNFα+ plasmablasts, that have been associated with aggressive reactivity in autoimmunity, were suppressed in the presence of tacrolimus." (PMID 28620390, 2017). "It stimulates a unique CD4+ inflammatory T-cell characterized by secretion of IL-17, tumor necrosis factor and IL-6, which are strongly associated with proinflammatory responses and severe autoimmunity." (PMID 23767933, 2013). "Many of the ancestral SNPs within the extended TNFα promoter have been associated with both autoimmune conditions and disease outcomes, however, the direct role of these variants on TNFα expression remains controversial." (PMID 22808100, 2012).
Autoimmunity (continued). "The remaining predictor genes have all been linked to the immune response or even to autoimmunity but, to date, this is the first evidence of their association to anti-TNF alpha treatment response." (PMID 19847310, 2009). "Furthermore, in 2 of the 7 patients with autoimmune conditions, there was a clinical suspicion of a possible association with a TNF inhibitor (infliximab and etanercept, respectively)." (PMID 38229275, 2024). "Maintaining tight regulation of TNFα may require more inhibitors like IL-10 for maturing women and be part of their susceptibility to autoimmunity." (PMID 36793337, 2023). "Paradoxically, both TNF excess and deficiency can exacerbate autoimmunity." (PMID 35104241, 2022). "We then asked whether a second hit could restore GC formation or induce pathogenic autoimmunity in TNF-deficient mice." (PMID 35104241, 2022). "We therefore asked whether excess TLR7 would induce GCs and pathogenic autoimmunity in Sle1 TNF–/– mice by introducing the Yaa locus that codes for an extra copy of TLR7 on the Y chromosome." (PMID 35104241, 2022). "Protein antigens were highly expressed in tissues involved in irAEs and were implicated in pathways that correlate with immunity–autoimmunity, such as “apoptosis”, “tumor necrosis factor-a (TNF-a) signaling”, the “interleukin-1 (IL-1) pathway”, and “Toll-like receptor (TLR) signaling”." (PMID 34771441, 2021). "As with IFN-γ, aberrant TNF-α signaling is associated with a variety of autoimmune disorders." (PMID 24672527, 2014). "In this regard, we hypothesized that autoimmunity caused by TNF-α 308 G/A mutation can be a contributing factor in the etiopathogenesis of SS." (PMID 24891849, 2014). "Likewise, it is important to know that evolutionary mechanisms have been developed for the production of TNF-α regulatory mechanisms, and their disruption can lead to an increase in action and be associated with autoimmunity." (PMID 22482039, 2012). "Because of the key pathogenic role of autoimmunity in these diseases, in this study we sought to evaluate TNFα production by a readily available source of immune cells (namely, peripheral blood mononuclear cells (PBMCs)) taken from controls and from patients with cutaneous lupus or DM." (PMID 22217359, 2012). "In some of these diverse rodent and human models of autoimmunity, the underlying mechanism of TNF’s therapeutic effect has been traced to various genetic and functional errors in the proteasome or proteasome-activated transcriptional factor NFκB (nuclear factor-κB) signaling pathway." (PMID 22905105, 2012). "This may be the case of TNFα, which is implicated in many autoimmune disorders." (PMID 36793337, 2023). "Although baseline predisposition of patients for fungal infections due to the autoimmune disorders, concomitant immunosuppressive therapies and geographical location need to be considered, Aspergillus, Candida and Cryptococcus infections are generally associated with the use TNF-a inhibitors." (PMID 33053052, 2020). "In line with this hypothesis, gene knockout studies, aimed at investigating the miR-146a function, showed that deficiency of this miRNA may lead to an excessive IL-6 and TNF-α production, hyperresponsiveness to bacterial lipopolysaccharide (LPS), chronic inflammation, and spontaneous autoimmunity." (PMID 32210951, 2020). "Importantly, after multiple testing correction, GC4 and GC7 were found to be significantly enriched in genes that are involved in immune-related pathways strongly associated with the autoimmunity etiopathogenesis like the TNFα (PFDR = 0.02) and INFγ cytokine pathways (PFDR = 0.02), respectively." (PMID 28982122, 2017). "Furthermore, imbalanced production of either IFN-I or TNF-α is linked to autoimmunity." (PMID 26709698, 2015).
Autoimmunity (continued). "TNF-α has been directly and indirectly linked to neoplasia and is involved not only in maintenance and homeostasis of the immune system, inflammation, and host defence, but also in pathological processes such as chronic inflammation, autoimmunity, and malignant disease." (PMID 24666463, 2014). "Studies have shown that IL23 promotes inflammatory responses by inducing the production of IL17, IL6, IL8, and tumor necrosis factor-α and that it regulates the amplification and the stability of Th17 lymphocytes, which are associated with strong pro-inflammatory responses and severe autoimmunity." (PMID 23840727, 2013). "In the context of autoimmunity and alloimmunity, TNF produced by T cells correlated with adverse outcomes." (PMID 40279312, 2025). "Several theories have been proposed to explain the development of autoimmunity during anti-TNF therapy." (PMID 40861456, 2025). "In conclusion, we identify Mac‐InflamAP as a disease‐specific inflammatory macrophage subpopulation that integrates TNF‐mediated MEL inhibition with enhanced antigen presentation to T cells, thereby sustaining vitiligo‐associated autoimmunity." (PMID 41498037, 2025). "Although a causal relationship remains controversial, the implication is that TNF has a complex role – its blockade can precipitate autoimmunity (e.g. lupus-like syndromes, vasculitis, and rarely dermatomyositis)." (PMID 40861474, 2025). "Conversely, numerous cases of myeloid leukemia have been documented in patients with CD or other autoimmune conditions who were treated solely with anti-TNF drugs or had brief prior exposure to azathioprine." (PMID 39949431, 2025). "Inhibitors of TNF, including infliximab, adalimumab, and etanercept, are widely employed therapies for the treatment of many autoimmune disorders." (PMID 40279312, 2025). "The immunogenicity towards TNFα inhibitors agents has been demonstrated with adalimumab as well, although in the context of other autoimmune disorders such as rheumatoid arthritis and hidradenitis suppurativa." (PMID 38474034, 2024). "Systematic monitoring for autoimmunity in inflammatory rheumatism patients receiving anti-TNF therapy reported rates of 20-60% for ANA, 15-20% for anti-DNA, and 15-20% for anti-histones." (PMID 39628740, 2024). "IL-5, IL-6, IL-13, IL-17, IL-23, and TNF-α are targetable with biologics developed for spontaneous autoimmunity, and our data broadly support the prospective investigation of these inhibitors for patients with irAEs." (PMID 39403935, 2024). "Conversely, the same IL-23 polymorphism was linked with statistical significance to an increased susceptibility to paradoxical psoriasiform reactions during anti-TNF therapy in patients with psoriasis or other autoimmune conditions." (PMID 38474034, 2024). "Elevated levels of pro-inflammatory cytokines such as IL-6, TNF-α, and IL-1β are frequently observed in adenomyosis, creating an environment conducive to autoimmunity." (PMID 39518312, 2024). "Anti-cytokine therapies such as TNF-α inhibitors are well-tolerated treatments for autoimmunity, making them attractive choices for synergistic dual therapy with other immune or β-cell regeneration therapies." (PMID 39411715, 2024). "TNF inhibitors are the mainstay treatment options for autoimmune and autoinflammatory diseases, and autoimmunity is predominantly a feature of type 1 DM." (PMID 38842591, 2024). "Analyses of transcriptional networks in autoimmunity have suggested that TNF-α and type I IFNs oppose each other molecularly." (PMID 39688922, 2024). "It is widely recognized that proinflammatory cytokines such as interleukins 1 (IL-1), interleukin 6 (IL-6), and tumor necrosis factor alpha (TNF-α) play a crucial role in promoting autoimmunity, persistent inflammation, and joint damage." (PMID 38256854, 2023).
Autoimmunity (continued). "Given the profound effects of manipulating TNF-TNFRs signaling in an autoimmunity context reported here and in literature, we consider this pharmacological approach to have high relevance for future research into MS treatment." (PMID 37138340, 2023). "TNF can either promote or modulate autoimmunity; however, it has been shown to be upregulated in SLE patients compared to healthy controls and is correlated with disease activity." (PMID 37370001, 2023). "By inhibiting TNF-a from binding to its receptor sites, the pro-inflammatory cytokine effects of TNF-a involved in inflammation, autoimmunity, and malignancy can be prevented, as the activation of these cytokine effects is dependent on TNF-a signaling." (PMID 37511975, 2023). "IL-1β has many biological functions, which are closely related to pain, inflammation, and autoimmunity, and is involved in neuroprotection, tissue remodeling and repair, and the regulation of IL-6 and TNF-α, etc.." (PMID 37109624, 2023). "Immunoregulatory cytokines, including tumor necrosis factor (TNF) and FasL, control immune-related events and are critically involved in pathophysiological processes such as autoimmunity and cancer." (PMID 37392849, 2023). "The results of the sensitivity analyses among patients with longer duration of anti-TNFα therapy or with the most prevalent autoimmune condition (RA) were consistent with the main findings." (PMID 36902722, 2023). "IL-15 induces the synthesis of certain cytokines that participate in autoimmunity like, for example, TNF-α and IL-1β, by enhancing the maintenance of CD-8 memory T-cell through the inhibition of self-tolerance." (PMID 37206670, 2023). "Inflammatory signaling is; however, intricate and their mediators including TNF, IL-1β, IL-6, and interferons often co-occur in conditions such as aging, cancer, and autoimmunity." (PMID 36968066, 2023). "IL-17 stimulates the production of multiple cytokines, such as IL-1β, IL-6, tumor necrosis factor (TNF) -α, and TGF-β, which cause and exacerbate inflammation and play an important role in inflammation, immunity, and autoimmunity." (PMID 37231328, 2023). "Local injection of CFA resulted in an increase of TNF-α, IL-1β, and IL-6 levels due to activation of autoimmunity cells which aggravated complete inflammation." (PMID 35193490, 2022). "There is a limitation to the beneficial effects of anti-TNF-α agents, which seems to be related to their ability to induce autoimmunity by disrupting TNF-α normal immune regulation." (PMID 35328704, 2022). "TNF is mainly produced by innate immune cells and is a critical regulatory cytokine of autoimmunity." (PMID 36248435, 2022). "NK cells participate in autoimmunity by secreting IL-1, IL-5, IL-8, IL-10, tumor necrosis factor-α (TNF-α), and Interferon-γ (IFN-γ) to kill aging, virus-infected, and tumor cells." (PMID 36428567, 2022). "TNF is a well-established RA driver that regulates inflammation, autoimmunity, and joint destruction in RA patients’ joints." (PMID 36172378, 2022). "Th1 cells, generating interleukin (IL)-2, interferon-gamma (IFN-γ), and tumor necrosis factor-alpha (TNF-α), mainly take part in delayed-type hypersensitivity reactions and cell-mediated immune responses, such as autoimmune disorders." (PMID 35935951, 2022). "Kyoto Encyclopedia of Genes and Genomes (KEGG) pathway enrichment analysis revealed that the upregulated expressed genes were enriched in IL-17, TNF, toll-like receptor, and other signaling pathways involved in inflammatory response and autoimmunity." (PMID 36183130, 2022). "TNF-α is a multi-effect pro-inflammatory medium related to inflammation, infection, autoimmunity, and malignant diseases." (PMID 35327113, 2022). "TNF is a central proinflammatory cytokine that is involved in a variety of inflammatory states, including autoimmunity." (PMID 36035842, 2022). "TNF-α is a well-known pro-inflammatory factor, and plays various roles in driving chronic inflammation and autoimmunity." (PMID 35990363, 2022).